BHLHE41 (basic helix-loop-helix family member e41)
Diseases named in the same sentence as BHLHE41 in open-access papers (continued):
Sharing a sentence is not in itself a finding about the gene and the disease.
cancer (38 papers, 2004 to 2025). A tumor composed of atypical neoplastic, often pleomorphic cells that invade other tissues. "In an analysis of The Cancer Genome Atlas data, SNPs highly correlated with rs7132434 show allele-specific differences in BHLHE41 expression (trend P value=6.3 × 10−7)." (PMID 27384883, 2016). "The basic helix-loop-helix family member e41 (BHLHE41) is frequently dysregulated in tumors and plays a crucial role in malignant progression of various cancers." (PMID 38811952, 2024). "This genetic change can induce BHLHE41/DEC2 expression during cancer development under HIF-1α expression; however, in this study the direct effects of BHLHE41/DEC2 were not examined." (PMID 37511489, 2023). "The regulation of expression of multiple genes by BHLHE40 and BHLHE41 also has been reported to affect cancer development in apoptosis, epithelial mesenchymal transition, and hypoxic reaction." (PMID 34768959, 2021). "Deregulation of the basic helix‐loop‐helix family member e41 (BHLHE41) has been characterized as a marker of progression of several cancers." (PMID 32073238, 2020). "Some of the TFs that were downregulated in NLPs, including Esx1, Bhlhe41, and Dmrt1, have been reported to play critical roles in negatively regulating cancer cell and stem cell growth in other tissues." (PMID 28725177, 2017). "Dysregulation of BHLHE41 has been identified in a variety of cancers, which contributes to the formation and progression of tumors and may be used as a prognostic marker." (PMID 38811952, 2024). "Finally, it is unclear how BHLHE41/DEC2 discriminates between cancer and normal cells, that is why autophagic cell death happens only in cancer cells." (PMID 37511489, 2023). "Second, it is unclear how BHLHE41/DEC2 can induce autophagic cell death in early cancer cells." (PMID 37511489, 2023). "The top intracellular pathways of the 12 overlapping genes were associated with circadian rhythms and entrainment (Arntl, Cry2, Per2, Per3, Bhlhe41), the cell cycle (Cdkn1a, Wee1), the oxytocin signaling pathway (Cdkn1a, Rcan1), and transcriptional misregulation in cancer (Cdkn1a, Per2)." (PMID 33668521, 2021). "On the other hand, DEC2 (BHLHE41) expression varies between different types of cancer." (PMID 33089188, 2020). "BHLHE41/DEC2 has been reported to be both a cancer-suppressive and an oncogenic gene during cancer development." (PMID 37511489, 2023). "This might reflect the difference in cancer development background between NSCLC and SCLC, although the meaning of these genetic changes of BHLHE41/DEC2 is still unclear." (PMID 37511489, 2023). "The balance of BHLHE41 and BHLHE40 expression and their molecular interaction might influence their roles in cancer development." (PMID 34768959, 2021). "BHLHE41/DEC2 might have a critical function in cancer development but may not always be required for maintaining advanced tumors." (PMID 37511489, 2023).
degenerative diseases (2 papers, 2021). "These include Spon2, Adam19, Arntl, Cdkn1a, Cry2, Per2, Per3, Wee1, Rcan1, Slc41a3, Errfi1, and Bhlhe41, which are related to numerous cardiovascular and degenerative diseases of other organs as well as varying aging processes." (PMID 33668521, 2021).
psychiatric disease (2 papers, 2014 to 2024). "Of note, BD risk was also not enriched in the MAGMA analyses, suggesting that BHLHE41 (which was also identified with INRICH at the gene level and CSNK1E are primarily associated with treatment response and neither with pathogenesis of BD nor any other psychiatric disease risk studied." (PMID 39372797, 2024).
BHLHE41 also shares sentences with these, for which no sentence is quoted: infection (6 papers); acute myelogenous leukemia (3); head and neck squamous cell carcinoma (3); melanoma (3); autoimmune disease (2); esophageal cancer (2); lentivirus infection (2); Obesity (2); rheumatoid arthritis (2); acute leukemia (1); adenocarcinoma of the (1); advanced sleep phase syndrome (1); Alzheimer disease (1); Angelman syndrome (1); Anxiety (1); cervical cancer (1); Colon Cancer (1); epilepsy (1); Focal cortical dysplasia (1); glioma (1); insomnia (1); lupus nephritis (1); lymph-node metastasis (1); metabolic disorders (1); mood disorder (1); oral cancers (1); osteoarthritis (1); otitis media (1); ovarian serous adenocarcinoma (1); pancreatic ductal adenocarcinoma (1).
A further 14 diseases each share a sentence with BHLHE41 in 1 paper.